CEACAM6 (CEA cell adhesion molecule 6)
Diseases named in the same sentence as CEACAM6 in open-access papers (continued):
Sharing a sentence is not in itself a finding about the gene and the disease.
tumor (continued). "CEACAM1, CEACAM5, and CEACAM6 all have variable roles in tumor initiation, progression, and metastasis." (PMID 36741860, 2023). "Previous works revealed that overexpressed CEACAM6 resulted the alteration and reorganization of the extracellular matrix and reestablished a promoting tumor environment by means of signal transduction." (PMID 37249822, 2023). "We also found that serum CEACAM6 was increased in LUAD patients with tumor progression and reached the peak in LM." (PMID 36082960, 2023). "Specifically, MMP9, MMP13, MMP11, and CEMIP were positively associated with the tumor immune microenvironment, while SLPI, SLC2A1, SERPINB5, HK2, CEACAM6, and CEACAM5 were negatively associated with the tumor immune microenvironment." (PMID 37234801, 2023). "Overexpression of CEACAM6 promotes cancer progression via its effects on cell proliferation, migration, and invasion, as well as tumor cell metastasis." (PMID 37684602, 2023). "Recently, we demonstrated the therapeutic effect of delivery of siCEACAM6 into cells in the acidic tumor microenvironment using a PNA form of CEACAM6-specific siRNA (siCEACAM6) as a peptide vector." (PMID 37684602, 2023). "A tumor promoting protein, CEACAM6, was among the top three upregulated genes in HUVEC vPK (WT) cells under different serum conditions compared to HUVEC EV cells." (PMID 37852997, 2023). "CEACAM6 mAbs with paclitaxel treatment markedly decreased tumor growth by 40% to 80% compared to CEACAM6 mAbs alone and were more effective in CEACAM6-targeting albumin-based nanoparticles." (PMID 36230714, 2022). "Although the mechanisms by which CEACAM6 regulates EMT are poorly understood, it was shown that CEACAM6 acts as an oncogene by promoting EMT in different tumor types." (PMID 35328744, 2022). "Among the CEACAM family members, CEACAM-5 (CEA) and CEACAM-6 (NCA) play significant roles in tumor progression and metastasis." (PMID 35804808, 2022). "Further studies will evaluate if core-1 and/or extended core-1 O-glycans recognized by NEO-201 are attached to other specific tumor-associated proteins (beyond CEACAM5 and CEACAM6) expressed by the different types of tumors targeted by NEO-201." (PMID 36291783, 2022). "The first consisted of CEACAM5 and CEACAM6 expressing tumour cells, colonic stem cells with high expression of OLFM4 and HIST1H4C." (PMID 35860583, 2022). "Our scRNA sequencing demonstrated that LM tumor cells had elevated levels of CEACAM6 expression, present across cfRNA samples tested via qPCR in a validation cohort." (PMID 34625644, 2021). "The highest signal intensity was observed in the tumor with the dose of 10 mg/kg CEACAM6-mAb-IRDye800CW probe injection." (PMID 34221964, 2021). "The carcinoembryonic antigen-related cell adhesion molecule 6 (CEACAM6) induces epithelial-mesenchymal transition (EMT), which causes tumor cell invasion in PaCa patients." (PMID 34262595, 2021). "Of note, CEAMCAM6-targeting albumin-based nanoparticles have demonstrated efficacy in targeting CEACAM6 in anoikis-resistant tumour cells." (PMID 34830751, 2021). "Among the downregulated genes in LA-treated cells were RGCC, a cell cycle regulator; CYTOR, a long non-coding RNA that enhances proliferation; and CEACAM6, which is a cell adhesion molecule that promotes tumor progression." (PMID 33546321, 2021). "Western blot analysis and densitometry readings revealed that CEACAM6 is expressed in PDAC tissue samples with a tendency for increasing expression as the tumour diameter increases." (PMID 34207784, 2021). "The results showed that the anti-CEACAM6 probe can closely bind to the GC cells and can track the tumor in the MKN-45 cells derived GC mice model." (PMID 34221964, 2021). "The results showed that the positive rate of CEACAM6 was 66.29% (59/89) and 4.49% (4/89) in the tumor tissues and the adjacent tumor tissues, respectively, and the staining H-Score in tumor was 39.56 ± 6.01." (PMID 34221964, 2021).
tumor (continued). "We found that CEACAM6 (Lenti-CEACAM6) over expression led to a significant increase in the tumor volume in a time-dependent manner, as compared to the Lenti-NC group." (PMID 34221964, 2021). "Then, we checked the expression of these proteins in the subcutaneous tumor tissues and found that high CEACAM6 expression can also promote the expression of p-Src, p-PI3K, p-Akt, and MMP9 proteins in vivo." (PMID 34221964, 2021). "The hybridoma cells successfully survived under in vivo conditions and continuously released sufficiently high levels of CEACAM6 antibodies; moreover, they were capable of suppressing CEACAM6 expressing tumor cells viability." (PMID 32357523, 2020). "Here, we assessed a novel monoclonal antibody for its ability to direct ADCC activity of NK cells against cancer cells expressing an apparent tumor-associated variant of CEACAM-5 and CEACAM-6." (PMID 32637350, 2020). "Members of the carcinoembryonic antigen related cell adhesion molecule (CEACAM) family including CEACAM6 modulate immune response, tumor progression, metastasis and angiogenesis." (PMID 33170151, 2020). "We have now generated an anti-CEACAM6 scFv-Fc (IgG4) and will be evaluating anti-tumor activity in PDA mouse models." (PMID 31797958, 2019). "We have developed a therapeutic humanized monoclonal antibody to CEACAM6, which showed promising anti-tumor activity in a mouse xenograft model." (PMID 31797958, 2019). "Correlation matrix assessment for CEACAM6 across tumor and normal samples identified 667 genes positively correlating and 171 genes negatively correlating with CEACAM6, with a correlation score of >0.4 and P value < 0.05." (PMID 31797958, 2019). "CEACAM6 is involved in cell adhesion, proliferation, migration, and invasion, as well as tumour cell metastasis." (PMID 31474761, 2019). "Several previously known cancer-related genes, including PTPN22, BRIP1, and CEACAM6, were found as hubs in the tumor-related subnetworks." (PMID 30240439, 2018). "Inhibition the expression of CEACAM6 by antibodies or RNAi can repress tumor cell growth, adhesion, invasion and metastasis, resulting in improved survival of mice carrying tumors." (PMID 29137373, 2017). "The CEACAM6 vaccine induced T-lymphocyte and natural killer cell infiltration and inhibited tumor development in rat colon cancer." (PMID 28883649, 2017). "The ratio of CEACAM6 positivity was 84.4% (120/180) in patients with tumor size ≥5 cm, which was higher than the ratio in patients with tumor size <5 cm (32.8%, 84/256; p = 0.000)." (PMID 29137373, 2017). "The protein level of CEACAM6 is significantly correlated with tumor size, Lauren's classification, invasion depth, lymph node metastasis, distant metastasis, and TNM stage." (PMID 29137373, 2017). "In early-stage GC, the body’s immune response is strong enough to kill tumor cells despite the anti-apoptotic effect of CEACAM6, resulting in better OS." (PMID 28883649, 2017). "Previous studies have shown that CEA and CEACAM6 are markers of poor outcome and tumor recurrence in several types of cancers including CRC." (PMID 29262644, 2017). "CEACAM6-positive immune cells are more likely to interact with CEACAM6-positive tumors through homophilic and heterophilic intercellular adhesion, thus suppressing tumor development." (PMID 28883649, 2017). "Although CEACAM6 promotes tumor cell migration, invasion, and anti-apoptosis in vitro, the situation is different in vivo because of the presence of an immune system." (PMID 28883649, 2017). "Immunocytes express CEACAM6, which makes interactions between immunocytes and CEACAM6-positive tumor cells more likely through homophilic and heterophilic intercellular adhesion." (PMID 28883649, 2017). "Weak CEACAM6 staining was present in tumors with minor structural disorder, while strong CEACAM6 staining was observed in tumors with major structural disorder, suggesting CEACAM6 disrupts tumor cell polarity and inhibits cell differentiation." (PMID 28883649, 2017).
tumor (continued). "We demonstrate low background signal from unstained tumor tissue with strong and clear fluorescent signal from tissue samples that have been exposed to anti-CEACAM6 Alexa Fluor 488 conjugated antibody for 30 minutes at room temperature." (PMID 27421133, 2016). "A video recording of the CEACAM6 signal obtained from the resected gastric PDX tissue using the confocal probe offers a representation of the endoscopic visualization of tumor tissue." (PMID 27421133, 2016). "A correlation between the two data sets was observed, moreover a tumor negatively staining for CEACAM6 by IHC also showed minimal staining with the fluorescently conjugated reagent." (PMID 27421133, 2016). "A larger in-house tissue microarray generated at National University Hospital, Singapore, also showed a significant enrichment of CEACAM6 expression in tumor cores, p < 0.001." (PMID 27421133, 2016). "Their results show that CEACAM6 is more strongly expressed than CEA, and that expression of CEACAM6 is strongly dependent on the histologic tumor type." (PMID 25427744, 2015). "In summary, we generated a new mAb, AP11, which recognizes CEACAM6, and evaluated its ability to be used as a tool to recognize CEACAM6 expression as a tumor marker in human cancer cells and tissues." (PMID 25427744, 2015). "Overexpressed CEACAM6 in tumor tissues plays important roles in invasion, metastasis and anoikis resistance in a variety of human cancers." (PMID 25398131, 2014). "CEACAM6 is an intercellular adhesion molecule that is over-expressed in a wide variety of human tumours and represents an important determinant of cancer progression." (PMID 24625834, 2014). "The novel recombinant plasmid was able to silence functional genome CEACAM6, inhibit tumor invasion and metastasis." (PMID 23251258, 2013). "In conclusion, our study shows that CEACAM6 is focally overexpressed in a large fraction of human HNSCCs in situ and contributes to tumour growth and tumour initiating activity." (PMID 23021083, 2012). "Next, we examined the ability of CEACAM6 Dux (miR CEA Dux) transduced or control-transduced (miR Control) cells to establish tumours in a xenotransplant model." (PMID 23021083, 2012). "Whilst CEACAM6 clearly has the capacity to contribute to drug resistance and tumour recurrence it is clear that other factors also contribute to drug resistance and tumour recurrence." (PMID 23021083, 2012). "Next, we examined the effect of overexpressing CEACAM6 in Detroit 562 cells on tumour initiation and growth in vivo in our xenotransplant model." (PMID 23021083, 2012). "We now report that 4 weeks of daily treatment with BGT226 of mice bearing tumours derived from Detroit 562 cells selectively ablates CEACAM6-positive foci in the tumours." (PMID 23021083, 2012). "The effect of CEACAM6 on tumour growth and initiation is mediated via suppression of PI3K/AKT-dependent apoptosis of HNSCC in a xenotransplant model of HNSCC." (PMID 23021083, 2012). "Most significantly, we found the expression of CEACAM6 to be focally overexpressed in the patient tumours which was consistent with the focal expression of CEACAM6 observed in tumours derived from the Detroit 562 parental cell line." (PMID 23021083, 2012). "Immunohistochemistry confirmed that knock down of Ceacam6 persisted to the termination of the study in xenotransplanted tumours." (PMID 23021083, 2012). "CEACAM6 overexpressing SCC cells (Detroit 562 pLV101-CEACAM6) were able to initiate tumours with 1 × 104 cells whereas vector-infected control cells (Detroit 562 pLV101) required 1 × 105 cells to initiate a tumour." (PMID 23021083, 2012). "Image analysis revealed that, on average across all the tumour samples, 28% +/− 12% of the total tumour area was positive for CEACAM6 expression." (PMID 23021083, 2012). "Anti-apoptotic activity is commonly viewed as tumour promoting and hence the anti-apoptotic activity of CEACAM6 would suggest it has tumour promoting (oncogenic) activity." (PMID 23021083, 2012).
tumor (continued). "Earlier work by Duxbury, suggests that the major contribution of CEACAM6 to tumour growth and tumour initiating activity is mediated via suppression of anoikis." (PMID 23021083, 2012). "Significantly, overexpression of CEACAM6 in Detroit 562 cells was accompanied by a profound and significant decrease in the apoptotic index of tumour cells in vivo compared to control tumours." (PMID 23021083, 2012). "The role of CEACAM6 in tumour growth and chemotherapeutic sensitivity was then assessed in vivo and in vitro respectively." (PMID 23021083, 2012). "On the other hand, targeting CEACAM6 results in decreased tumor growth, and inhibits metastases in a mouse xenograft model." (PMID 20090913, 2010). "As observed with other cancer cell lines the tumour markers Ceacam6 as well as Ceacam1 were upregulated in cell line CaCo2." (PMID 21152443, 2010). "In the present study, we provide new insights into the multiplicity and diversity of CEACAM1, CEACAM5 and CEACAM6 expression and their functions in tumor development and progression." (PMID 20090913, 2010). "In contrast, CEACAM6 immunostaining of lymph node metastases from breast, colon, or lung tumors was similar to the primary tumor." (PMID 17201906, 2007). "CEACAM5 and CEACAM6 are commonly considered inert tumour markers, despite the discovery and documentation of their tumorigenic functions over the past two decades." (PMID 17576469, 2007). "All these results suggested that 131I radiolabeling preserved specificity, affinity and immunoreactivity of tinurilimab, and 131I‐tinurilimab may be applicable for the therapy of CEACAM6‐positve tumor (LUAD) or malignant pulmonary nodules." (PMID 40178153, 2025). "Thus, A549 and Huh7 were respectively employed in subsequent CEACAM6‐positive and CEACAM6‐negative tumor cells." (PMID 40178153, 2025). "Lastly, combining CEACAM6 expression with clinical parameters—such as tumor grade and receptor status—may enhance the predictive performance of future clinical models." (PMID 40936892, 2025). "Additionally, radionuclide‐labeled CEACAM6 antibody (131I‐tinurilimab) was demonstrably capable of significantly inhibiting tumor growth in CEACAM6‐positive xenograft tumor models." (PMID 40178153, 2025). "Additionally, we demonstrated the therapeutic efficacy of CEACAM6 gene silencing using a small-interfering RNA (siRNA) delivery platform in an acidic tumor microenvironment." (PMID 40282889, 2025). "Therefore, CEACAM6 is capable of reflecting the advancement of tumor more precisely and is appropriate to be utilized as a biomarker for the diagnosis or prognosis of LUAD as well as a cell surface PET tracer target." (PMID 40178153, 2025). "This metabolic adaptation may allow CEACAM6-high tumor cells to better withstand the metabolic stress imposed by cytotoxic chemotherapy." (PMID 40936892, 2025). "In addition, we observed a smaller tumor area derived from human GBC cells in mice injected with CEACAM6-expressing cells based on hematoxylin and eosin (HE) and Ku80 staining." (PMID 39468006, 2024). "CAR T-cells would physically eliminate CEACAM6-positive cells within the tumor burden." (PMID 38279989, 2024). "Interaction between CEACAM6 on human solid cancer cells and CEACAM1 on activated tumor-reactive T cells suppresses the antitumor function of T cells, and a humanized anti-CEACAM6 antibody, BAY 1834942, blocks this interaction and restores the antitumor activity of T cells in CEACAM6-positive tumors." (PMID 38796667, 2024). "However, CEACAM6 role is not only restricted to cancer progression, but this molecule can also act as an immune checkpoint inhibitor in tumours." (PMID 38342891, 2024). "Its mechanism of action involves selective binding to CEACAM6 on the tumor cell surface, thereby localizing urease, which converts endogenous urea into NH3 and CO2 with a net production of bicarbonate and hydroxyl ions and causes alkalinization of the extracellular tumor microenvironment (TME)." (PMID 38398062, 2024).
tumor (continued). "CEACAM6 ultimately regulates tumour cell growth, leading to resistance to 5‐fluorouracil." (PMID 39456119, 2024). "Interestingly, CEACAM6 expression was higher than traditional biomarker CEACAM5 (CEA) in CSF tumor cells." (PMID 36082960, 2023). "We discovered that patients with high tumor expression of ALDOB were associated with high levels of circulating CEA, prompting us to investigate whether CEACAM6 expression was correlated with ALDOB levels." (PMID 37816733, 2023). "Our previous single‐cell RNA sequencing data of CSF circulating tumor cell (CSF‐CTCs) from five LUAD‐LM patients indicated that CEACAM6 mRNA was significantly upregulated compared to normal CSF cells, and the immunohistochemistry staining also showed high expression of CEACAM6 in CSF‐CTCs." (PMID 36082960, 2023). "The high expression of CEACAM6 in CSF tumor cells indicates its potential in the LUAD‐LM diagnosis." (PMID 36082960, 2023). "The specific binding of NEO-201 to tumor-associated variants of CEACAM5 and CEACAM6 could be due to post-translational modifications (i.e., attachment of O-glycans to the protein structure of those proteins) occurring during the process of carcinogenesis." (PMID 36291783, 2022). "The fact that NEO-201 recognizes tumor-associated variants of CEACAM-5 and CEACAM-6 could be due to the post-translational modifications (i.e., glycosylation) occurring during the process of carcinogenesis." (PMID 35804808, 2022). "Moreover, we performed the immunofluorescence staining of the tumor-specific gene CEACAM6 for both in vivo tissue sections and organoids in culture." (PMID 35484598, 2022). "Furthermore, higher expression levels of the tumor marker CEACAM6 were verified via IHC staining in five patients in this cohort and three additional patients." (PMID 35974387, 2022). "CEACAM6, being important for cell adhesion during cancer progression, was detected to be upregulated in 3D culture, stressing the importance of growth conditions tumor cells are exposed to." (PMID 35565305, 2022). "The detection of CEACAM6 in tumor-associated cfRNA, but not in controls, was true despite variable clinical treatments." (PMID 34625644, 2021). "Tumor-associated cfRNA (e.g., CEACAM6, MUC1) was present in NSCLC LM patients’ CSF, but not in controls (CEACAM6 detection sensitivity 88.24% and specificity 100%)." (PMID 34625644, 2021). "DUSP4, as well as cell adhesion molecule CEACAM6, was reduced in LA-treated cells as well, which could be a protective response against tumor progression." (PMID 33546321, 2021). "In more detail, SIGLEC17P expression could be used by Tregs to circulate among all tissues; CD33, PCDH1, JAM2, CDHR3, and ITGA3 would orchestrate migration/retention in NI TDLNs; CADM1 in I TDLNS; and CEACAM6 in tumor." (PMID 32601304, 2020). "In addition, CEACAM6 over-expression in varied malignancies promoting cell invasion and metastasis, therefore, it represents a characteristic advantage of tumor cells which are responsible for an invasive phenotype." (PMID 31244774, 2019). "The present results using CEACAM6-targeting siRNA indicate that RNAi may effectively reduce CEACAM6 activity in vitro and induce antitumour effects in A549 human lung xenograft tumours." (PMID 31474761, 2019). "Increased expression of CEACAM6 promotes tumor metastasis, antiapoptosis, and angiogenesis in pts." (PMID 30809317, 2019). "At day 30, tumor growth suppression was >95% in the CEACAM6−/− vs. CEACAM6 +/+ tumors." (PMID 31797958, 2019). "Network analysis of downstream gene signatures revealed several hub genes such as SRC and DNM1L etc. which may mediating tumor promoting functions of CEACAM6." (PMID 29137373, 2017). "In addition to CEACAM6 expression, tumor stage was also a significant predictor of recurrence and overall survival (p < 0.001)." (PMID 29137373, 2017). "However, most tumor tissues were stained with strong CEACAM6 in advanced-stage GC and CEACAM6-positive tumor cells were detected in vascular and interstitial tissues." (PMID 28883649, 2017).